TFDP3 (transcription factor Dp family member 3)
Description:
Competitive inhibitor of E2F-mediated transactivation activity. Impairs E2F-mediated cell-cycle progression from G(1) to S phase.
Synonyms: CT30; DP4; HCA661; E2F-like
Tractability: No criterion of Open Targets' tractability assessment is met for any kind of drug.
Gene: Protein-coding gene on chromosome X (133,216,662 to 133,218,354, reverse strand). Ensembl gene ENSG00000183434.
Subcellular location: Nucleus; Cytoplasm
Subcellular location (Human Protein Atlas): Nuclear membrane; Nucleoplasm; Cytosol
Gene Ontology:
Molecular function: DNA-binding transcription factor binding; RNA polymerase II-specific DNA-binding transcription factor binding; transcription regulator inhibitor activity; DNA-binding transcription factor activity, RNA polymerase II-specific; RNA polymerase II transcription regulatory region sequence-specific DNA binding
Biological process: DNA damage response; negative regulation of G1/S transition of mitotic cell cycle; regulation of transcription by RNA polymerase II; regulation of cell cycle; regulation of DNA-templated transcription; regulation of gene expression
Cellular component: cytoplasm; cytosol; nuclear membrane; nucleoplasm; chromatin; nucleus; transcription regulator complex
Homologues: Orthologues: chimpanzee TFDP3 (95% identical), macaque TFDP3 (86% identical), Drosophila melanogaster Dp (34% identical), Caenorhabditis elegans dpl-1 (30% identical). Paralogues in human: TFDP1 (75% identical), TFDP2 (51% identical).
Diseases named in the same sentence as TFDP3 in open-access papers:
TFDP3 is named in the same sentence as 34 diseases in open-access papers, as found by Europe PMC text mining. Sharing a sentence is not in itself a finding about the gene and the disease. The quoted sentences say what the papers report.
breast carcinoma (6 papers, 2017 to 2021). "Since TFDP3 represses the transcriptional activity of downstream genes by preventing the E2F1 heterodimer from entering the nucleus, we speculated that the expression of TFDP3 in breast cancer would cause transcriptional repression of certain genes downstream of E2F1." (PMID 28114432, 2017). "TFDP3 is expressed in breast cancer cell lines, but it is preferentially expressed in mesenchymal then in luminal types of breast cancer." (PMID 34745961, 2021). "As we all know, transcriptional master regulators exert a critical role in cancer genetic networks, and TFDP3 and other transcription factors have been identified in gene regulatory network of primary breast cancer." (PMID 34745961, 2021). "The results show that TFDP3 promoted the chemotherapy-induced cell autophagy process in breast cancer cells." (PMID 30235236, 2018). "In order to determine the expression and subcellular localization of TFDP3 in breast cancer, we performed Western Blot analysis on MDA-MB-231, MCF-7, SK-BR-3 and MCF-10A cell lines." (PMID 30235236, 2018). "Previous study screened and selected appropriate siRNA sequences in MDA-MB-231 breast cancer cells which showed satisfactory response to TFDP3 knockdown." (PMID 30235236, 2018). "In this study, we investigated the expression of TFDP3 in a variety of breast cancer cell lines and its subcellular localization." (PMID 30235236, 2018). "In this study, we found that TFDP3 was widely expressed in breast cancer cells and, identified its subcellular localization in both the nucleus and the cytoplasm." (PMID 30235236, 2018). "To further clarify the mechanism by which TFDP3 promotes tumor growth, we also studied the apoptosis rate and autophagy regulation of the TFDP3-knockdown breast cancer cell." (PMID 30235236, 2018). "The results of the flow cytometry test show that, following etoposide treatment, the apoptosis rate of breast cancer cell line MDA-MB-231 significantly increases after TFDP3-siRNA transfection." (PMID 30235236, 2018). "In this study, our group investigated the expression of TFDP3 in mononuclear cell samples from a variety of tissue-derived malignant tumors, breast cancer and benign breast lesions." (PMID 30235236, 2018). "To explore how TFDP3 affects autophagy in breast cancer, we transfected the breast cancer cell line MDA-MB-231 with TFDP3-siRNA." (PMID 30235236, 2018). "TFDP3 is a new, promising candidate for transcriptional regulation in breast cancer, although it was first identified in hepatocellular carcinoma." (PMID 28114432, 2017). "Here, we demonstrate that TFDP3 is expressed in a variety of malignancies, normal testis tissue and breast cancer cell lines and thus provide evidence that TFDP3 is a cancer-testis antigen." (PMID 28114432, 2017). "Since immunohistochemistry revealed that TFDP3 is expressed in breast cancer tissues, we sought to determine the expression level of TFDP3 in breast cancer cell lines." (PMID 28114432, 2017). "This is the first time that TFDP3 was reported to be expressed in breast cancer, although TFDP3 was reported to be present in U2OS, HEK293, H1288, MCF-7 and HeLa cell lines." (PMID 28114432, 2017). "Our data showed that TFDP3 was highly expressed in mesenchymal cell line but less expressed in luminal type of breast cancer." (PMID 28114432, 2017). "Taken together, we proved that knockdown of TFDP3 in mesenchymal types of breast cancer would decrease mesenchymal markers while increase luminal markers, and this process would affect the migration capacity of cells." (PMID 28114432, 2017). "The rate of TFDP3 expression was 46.88% in all of the invasive ductal carcinoma cases, indicating that TFDP3 is present in clinical breast cancer samples." (PMID 28114432, 2017). "TFDP3 is located on the X chromosome, as the same as other cancer-testis antigens, only expressed in melanoma, hepatic carcinoma, breast cancer and T lymphocytic leukemia and other malignant tumor cells and normal testicular tissue." (PMID 28797103, 2017).
breast carcinoma (continued). "Collectively, our data provide evidence that TFDP3 is expressed in breast cancer, that it is a member of the cancer-testis antigen family and that it is involved in epithelial-mesenchymal transition." (PMID 28114432, 2017). "A new peak was detected by flow cytometry in the FL1 channel after antibody staining, further confirming that TFDP3 is expressed in breast cancer cell lines." (PMID 28114432, 2017). "Recently, TFDP3 and some other transcription regulators were found to have a critical role in the gene interaction network in breast cancer." (PMID 28114432, 2017). "We performed an overexpression experiment of TFDP3 in luminal type of breast cancer (T-47D) utilizing overexpression plasmid, and our data showed that the expression level of TFDP3 was upregulated to 12.2 fold after overexpression plasmid transfection." (PMID 28114432, 2017). "Interestingly, it has been reported that TFDP3 is expressed in breast cancer and acts as a transcription factor during epithelial-mesenchymal transition." (PMID 34745961, 2021). "This suggests that less expression of TFDP3 in breast cancer cells might up-regulate the sensitivity to chemotherapy drugs and eventually lead to cell apoptosis." (PMID 30235236, 2018). "Moreover, it can be inferred that TFDP3 also plays an important role in the process of drug resistance of breast cancer, which can prevent chemotherapy-induced apoptosis of tumor cells." (PMID 30235236, 2018). "Consequently, cancer-testis antigen TFDP3 plays a very significant regulatory role in the emergence of drug resistance in breast cancer and other solid malignant tumor cells." (PMID 30235236, 2018). "We previously reported that breast cancer with high expression of TFDP3 was much more invasive and this trait could be reversed once TFDP3 was knockdown in breast cancer cell line MDA-MB-231." (PMID 30235236, 2018). "However, in the breast cancer tissues, various levels of TFDP3 was identified in nearly half of the patients." (PMID 30235236, 2018). "Expressions of TFDP3 in breast benign disease and breast cancer tissues." (PMID 30235236, 2018). "The question whether TFDP3 is expressed in other breast cancer cell lines or in normal breast cell lines, however, was still unanswered." (PMID 28114432, 2017). "Collectively, these data suggest that TFDP3 is expressed in breast cancer cell lines." (PMID 28114432, 2017). "Taken together, our data suggested that induced expression of TFDP3 in luminal breast cancer cells (T-47D) would increase mesenchymal markers while correspondingly decrease luminal markers, and this process significantly increases their migratory and invasive activity." (PMID 28114432, 2017). "To further confirm our speculation that TFDP3 is expressed in breast cancer cell lines, we carried out immunofluorescence and flow cytometry." (PMID 28114432, 2017). "As for HER2 staining (p = 0.038), the rate of TFDP3 expression was 24.14% in the HER2-negative group (14 in 58 cases) and 50% in the HER2-positive group (19 in 38 cases), indicating that HER2 amplification might lead to TFDP3 activation in breast cancer." (PMID 28114432, 2017). "Our data revealed that TFDP3 is expressed in breast cancer tissue and breast cancer cell lines." (PMID 28114432, 2017). "Accordingly, silencing TFDP3 may hinder the exacerbation of breast cancer by blocking the EMT." (PMID 34745961, 2021). "And in a large sample size of breast cancer microarray analysis, the expression of TFDP3 was related with HER2-overexpression subtype of breast cancer, it indicated that TFDP3 may play an important role in the diagnosis and drug-resistant of HER2-overexpression breast cancer." (PMID 30235236, 2018).
breast carcinoma (continued). "Thus, we hypothesized that TFDP3 may play a biological role in the proliferation, apoptosis, migration and metabolism of breast cancer cell line MDA-MB-231." (PMID 30235236, 2018). "Thus, the intracellular localization of TFDP3 in both the nucleus and the cytoplasmic of breast cancer cells indicates that TFDP3 may play a biological role in cell proliferation, apoptosis, migration and metabolism." (PMID 30235236, 2018). "TFDP3 is another MET-related gene which can also induce apoptosis and autophagy in breast cancer and prostate cancer." (PMID 32309437, 2020). "After treatment with 1μM etoposide for 24 hours in breast cancer cell line MDA-MB-231, the expression of TFDP3 and LC3 was up-regulated." (PMID 30235236, 2018). "Being different with the other TFDP family members, TFDP3 is a human-specific TFDP family of protein molecules, and expressed only in malignant tumor cells such as melanoma, liver cancer, breast cancer and T lymphocytic leukemia, also in normal testis tissues." (PMID 28797103, 2017). "We performed a knockdown experiment of TFDP3 in mesenchymal type of breast cancer (MDA-MB-231) utilizing siRNA, and our data showed that TFDP3 was knocked down after siRNA transfection (relative amount 0.0012 vs 1.0)." (PMID 28114432, 2017). "TFDP3 was found to participate in the EMT process, as proven by the overexpression and silencing experiments performed on breast cancer cell lines." (PMID 28114432, 2017). "To further determine the expression status of TFDP3 in breast cancer cell lines, we selected MDA-MB-231 (basal type of breast cancer, mesenchymal phenotype) and T-47D (luminal type of breast cancer) cell lines." (PMID 28114432, 2017). "The rate of TFDP3 expression was 46.88% in invasive ductal carcinoma (BR486), providing a platform for targeted therapy for breast cancer." (PMID 28114432, 2017). "For abnormal breast tissues, TFDP3 is expressed only in breast cancer rather than in other benign breast lesions." (PMID 30235236, 2018). "The statistical analysis revealed that TFDP3 is more likely expressed in breast cancers rather than other benign breast lesions." (PMID 30235236, 2018). "As TFDP3 only expressed in breast cancer and not in other non-breast cancer diseases, it was concluded that TFDP3 expression only correlates with certain kinds of pathological diagnosis of breast disease." (PMID 30235236, 2018). "Because TFDP3 was correlated with the clinical N stage, we asked whether TFDP3 expression was correlated with the EMT phenotype in breast cancer cells." (PMID 28114432, 2017). "The role of TFDP3 in EMT in breast cancer, however, has not been identified yet." (PMID 28114432, 2017). "In terms of survival rates (p = 0.671), the data revealed that the expression level of TFDP3 might not affect the clinical outcome of breast cancer or that TFDP3 might not be an independent prognostic factor for breast cancer." (PMID 28114432, 2017). "Therefore, it was necessary to highlight the role of TFDP3 in breast cancer since TFDP3 suppresses gene expression independent of the retinoblastoma tumor suppressor protein pathway." (PMID 28114432, 2017).
hepatocellular carcinoma (4 papers, 2017 to 2021). A malignant tumor that arises from hepatocytes. "Regarding cancer therapy opportunity, the transduction of dendritic cells with recombinant adenovirus-encoding TFDP3 can activate autologous cytotoxic T lymphocytes to target hepatoma cells." (PMID 34745961, 2021). "We constructed a recombinant adenovirus-expressing TFDP3 and then transduced immature DCs; excitingly, the approach can help to induce DC maturation and these DCs can activate T cells to target hepatoma." (PMID 34745961, 2021). "In this study, we explored the expression of TFDP3 in normal liver and liver cancer tissues, and in the immortalized hepatocyte line L-02 and hepatocellular carcinoma cell line HepG2, to discuss the role and mechanism of TFDP3 in cell cycle." (PMID 28797103, 2017). "This study confirmed that TFDP3 is expected to be a potential target for the treatment of hepatic carcinoma." (PMID 28797103, 2017). "Human transcription factor dimerization partner family member 3 (TFDP3) was first identified in hepatocellular carcinoma in 2002 by Chen WF, who used a method involving serological analysis of recombinant cDNA expression libraries." (PMID 28114432, 2017). "Also, TFDP3 participates in hepatocellular carcinoma through interfering with HIF-2α and modulating the cell apoptosis mediated by the E2F1 pathway." (PMID 34745961, 2021). "The TFDP3 mRNA is highly expressed in certain types of cancers such as hepatocellular carcinoma." (PMID 34745961, 2021). "Thus, as a pivotal collaborative protein of E2F, TFDP3 exerts a crucial role in diseases, particularly in cancers as detected in immortalized human hepatocyte line L-02 and hepatocellular carcinoma cell line HepG2 at mRNA and protein level." (PMID 34745961, 2021). "This study demonstrates that TFDP3-knockdown siRNAs can block the cell cycle progression of L-02 and HepG2 cell lines, suggesting that TFDP3-siRNA is potentially useful in the treatment of malignant tumors such as hepatocellular carcinoma." (PMID 28797103, 2017). "In this study, the expression of TFDP3 in normal liver tissue was negative, and the expression of TFDP3 in hepatocellular carcinoma and testis was positive." (PMID 28797103, 2017). "The result showed that the expression of TFDP3 molecule is negative in normal liver tissue, but positive in immortalized human hepatocyte cell line, and the expression level is lower than in hepatocellular carcinoma cell line." (PMID 28797103, 2017).
prostate carcinoma (3 papers, 2017 to 2021). A carcinoma that arises from epithelial cells of the prostate gland. "Furthermore, a research suggested that TFDP3 is involved in prostate cancer cell survival by suppressing apoptosis." (PMID 34745961, 2021). "Interestingly, a study of TFDP3 in prostate cancer emphasized that TFDP3 was coexpressed with E2F1." (PMID 34745961, 2021). "Therefore, reducing the level of TFDP3 is an ideal way to restore the E2F physiological function and thereby recover the normal apoptosis rate in cells, which could improve the survival of patients with prostate cancer and other carcinomas." (PMID 34745961, 2021).
T-cell acute lymphoblastic leukemia (3 papers, 2017 to 2021). Acute lymphoblastic leukemia of T-cell origin. "Intriguingly, TFDP3 confers chemoresistance in minimal residual disease within childhood T-cell acute lymphoblastic leukemia, and downregulation of TFDP3 by RNA interference sensitizes cancer cells to combinational chemotherapy." (PMID 34745961, 2021). "TFDP3 overexpression confers chemo resistance in minimal residual disease in childhood T-cell acute lymphoblastic leukemia." (PMID 32429253, 2020).
adenosis (2 papers, 2017 to 2018). "We did not detect TFDP3 expression in normal breast tissue or a variety of benign breast diseases such as plasma cell mastitis and breast adenosis." (PMID 30235236, 2018).
leukaemia (2 papers, 2008 to 2017). "Our study demonstrates that TFDP3 contributes to MDR pattern in MRD by suppressing E2F1-induced apoptosis, and targeting TFDP3 may provide a promising strategy for improving leukemia treatment and for overcoming DNA damage based chemoresistance in residual cancer." (PMID 27902457, 2017).
breast diseases (1 paper, 2018). "The expression of TFDP3 and the correlation between the expression of TFDP3 and the pathologic diagnosis of 47 cases of breast diseases were analyzed by chi-square test and rank-sum test." (PMID 30235236, 2018).
ductal carcinoma (1 paper, 2017). "TFDP3 was expressed in the MDA-MB-231 (adenocarcinoma) and HCC1954 (ductal carcinoma) cell lines, both at the mRNA and protein levels." (PMID 28114432, 2017).
gastric adenocarcinoma (1 paper, 2020). "Next, 10 ERGs associated with prognosis of gastric adenocarcinoma patients are screened out by univariate Cox regression, and 6 pivotal prognostic ERGs (MMP8, MMP11, TFDP3, MYB, F2, and CNTN1) are identified through multivariate Cox regression." (PMID 32309437, 2020).
intraductal carcinoma (1 paper, 2017). "As for the histological types (p = 0.131), we found that the rate of TFDP3 expression was 39.86% in invasive ductal carcinoma (57 in 143 cases), but that TFDP3 was not expressed in invasive lobular carcinoma (0 in 4 cases), mucinous carcinoma (0 in 2 cases) or intraductal carcinoma (0 in 1 cases)." (PMID 28114432, 2017).
liver cancer (1 paper, 2017). An epithelial or non-epithelial malignant neoplasm that arises from the liver. "TFDP3, also known as HCA661, was a cancer-testis antigen (CTA), which originally identified by Dr. Chen in 2002 from human primary liver cancer tissue through SEREX technology." (PMID 28797103, 2017).
metastatic disease (1 paper, 2017). "Our data showed that TFDP3 confers chemoresistance in MRD within childhood T-ALL, indicating that targeting TFDP3 is a potential strategy for overcoming chemoresistance in minimal residual cancer cells, and stop progression to relapse and metastatic disease." (PMID 27902457, 2017).
pancreatic cancer (1 paper, 2020). "The transcription factors NFYC, TFDP3, POLE3 and E2F4 are closely linked to hub genes in pancreatic cancer." (PMID 32587798, 2020).